ARL6IP5 (ARF like GTPase 6 interacting protein 5)
Diseases named in the same sentence as ARL6IP5 in open-access papers:
ARL6IP5 is named in the same sentence as 54 diseases in open-access papers, as found by Europe PMC text mining. Sharing a sentence is not in itself a finding about the gene and the disease. The quoted sentences say what the papers report.
gastric cancer (12 papers, 2012 to 2025). A primary or metastatic malignant neoplasm involving the stomach. "ARL6IP5 was implicated as a potent inhibitor of cisplatin-resistance through the CK2-XRCC1 pathway in gastric carcinoma." (PMID 35293383, 2022). "For instance, in gastric cancer, ARL6IP5 is significantly downregulated in cancerous tissues compared to matched non-cancerous mucosa." (PMID 40253526, 2025). "Previous studies on gastric carcinoma and fibroblasts, ARL6IP5 was found to be significantly lower in malignantly transformed cells compared to their normal counterparts." (PMID 35293383, 2022). "Previously, ARL6IP5 was reported to play a pivotal role in gastric carcinoma progression." (PMID 35293383, 2022). "Thus, ARL6IP5 has been regarded as an effective biomarker for gastric cancer." (PMID 40253526, 2025). "Similarly, ARL6IP5 was shown to reverse cisplatin-resistance in gastric cancer." (PMID 40253526, 2025). "Mechanistic studies have shown that ARL6IP5 insufficiency and up-regulation of matrix metalloproteinase-2 (MMP-2) can increase tumor micro vessel density in gastric cancer." (PMID 40253526, 2025). "Recently we reported that JWA, an ADP-ribosylation-like factor 6 interacting protein 5 (ARL6ip5), was both prognostic for overall survival and predictive for platinum-based treatment of gastric cancer." (PMID 23285001, 2012). "Notably, they discovered that ARL6IP5 had contrasting effects on XRCC1 in gastric carcinoma cells compared to their normal counterparts; on gastric carcinoma cells ARL6IP5-OE decreased XRCC1 levels, while in their normal counterparts ARL6IP5-OE increased XRCC1 levels." (PMID 35293383, 2022).
breast carcinoma (11 papers, 2012 to 2026). "Literature indicates that ARL6IP5 is also associated with angiogenesis, cell proliferation, apoptosis, metastasis, and resistance to chemotherapy in gastric, ovarian, and breast cancer." (PMID 41550766, 2026). "Previous studies have shown that ARL6IP5 downregulation caused increased cell migration and invasion in malignant melanoma, osteosarcoma, cervical carcinoma, esophageal carcinoma, and breast carcinoma." (PMID 35293383, 2022). "Arsenic trioxide up-regulates the expression of ARL6IP5 by stimulating the production of reactive oxygen species in a dose-dependent manner, and ARL6IP5 induces apoptosis and loss of mitochondrial transmembrane potential in breast cancer cells." (PMID 40253526, 2025). "The activation of p38 MAPK contributes to ARL6IP5-promoted tubulin polymerization which also improves the sensitivity of breast cancer cells to arsenic trioxide." (PMID 40253526, 2025). "In several cancers, such as skin cancer, pancreatic cancer, and breast cancer, the tumor suppressive role of ARL6IP5 was found to be mediated via its inhibitory effects on MAPK signaling pathway and JNK pathways." (PMID 40253526, 2025). "The tumor suppressor roles of ARL6IP5 have also been observed in other common cancers, including esophagus, liver cancer, breast cancer, cervical cancer, and skin cancer." (PMID 40253526, 2025). "In breast cancer, ARL6IP5 is involved in the estrogen receptor-related signal transduction pathways." (PMID 40253526, 2025). "In breast carcinoma cells, ARL6IP5 downregulation reduced apoptosis via the MAPK signaling pathway." (PMID 35293383, 2022). "We also identified some category 2 genes such as ARL6IP5, RAET1E, and ANO7 that could be crucial for breast cancer development and prognosis." (PMID 25803781, 2015). "We also identified some genes such as ARL6IP5, RAET1E, and ANO7 that could be crucial for breast cancer development and prognosis." (PMID 25803781, 2015).
Parkinson disease (5 papers, 2022 to 2025). A progressive degenerative disorder of the central nervous system characterized by loss of dopamine producing neurons in the substantia nigra and the presence of Lewy bodies in the substantia nigra and locus coeruleus. "Arl6IP5 is implicated in the progression of Parkinson's disease (PD)." (PMID 40209949, 2025). "ARL6IP5 overexpression reduces α-synuclein aggregate burden and improves cell survival in an A53T model of Parkinson’s disease." (PMID 37445677, 2023). "To address this, in our present study, we identified a novel regulator (ARL6IP5) of neuronal autophagy and showed that the level of ARL6IP5 decreases in the brain with age and in Parkinson’s disease in mice and humans." (PMID 37445677, 2023). "The extended studies we conducted on understanding the role of ARL6IP5 in Parkinson’s disease and aging revealed it was downregulated in the brain as it aged, and this downregulation was even more pronounced in PD animal, human, and cellular models." (PMID 37445677, 2023). "Additionally, we assessed the level of ARL6IP5 in the brain lysates of 6-OHDA-induced Parkinson’s disease in mice." (PMID 37445677, 2023).
diabetes (4 papers, 2013 to 2024). "This transcription factor leads to the inhibition of FHL1, IARS2, ARL6IP5, PSIP1 and PRPS1, some of which have been implicated in processes that are involved in the progression of different conditions leading to diabetes." (PMID 26302420, 2015).
hepatocellular carcinoma (4 papers, 2015 to 2025). A malignant tumor that arises from hepatocytes. "For instance, functional studies have shown that down-regulation of ARL6IP5 in hepatocellular carcinoma (HCC) and non-small cell lung cancer can promote tumor invasion and predict a poor prognosis." (PMID 40253526, 2025).
ovarian carcinoma (4 papers, 2019 to 2025). A malignant neoplasm originating from the surface ovarian epithelium. "In ovarian cancer, ARL6IP5 appeared to exert a tumor suppressive role, and as such, recombinant ARL6IP5 protein was demonstrated to sensitize the ovarian cancer cells to cisplatin." (PMID 40253526, 2025). "Nevertheless, ARL6IP5 can also suppress DNA repair and promote apoptosis pathways in ovarian carcinoma cells." (PMID 38879526, 2024).
cervical carcinoma (3 papers, 2012 to 2022). A carcinoma arising from either the exocervical squamous epithelium or the endocervical glandular epithelium. "Therefore, plasma exosomal RGS18 may be more associated with cervical cancer development and progression than the other three mRNAs (KIF2A, ARL6IP5, and DAPP1)." (PMID 34827689, 2021).
esophageal cancer (3 papers, 2014 to 2022). A primary or metastatic malignant neoplasm involving the esophagus. "In esophageal carcinoma cells, ARL6IP5-OE induced apoptosis through Caspase-8 and Caspse-9, the key executioners of the extrinsic and intrinsic apoptosis pathways, respectively." (PMID 35293383, 2022).
leukemia (3 papers, 2013 to 2025). A malignant (clonal) hematologic disorder, involving hematopoietic stem cells and characterized by the presence of primitive or atypical myeloid or lymphoid cells in the bone marrow and the blood. "A meta-analysis showed that increased expression of ARL6IP5 is related to worse overall survival and event-free survival of leukemia patients, and ARL6IP5 overexpression is an independent risk factor of poor survival in leukemia patients." (PMID 40253526, 2025).
bladder cancer (2 papers, 2022 to 2025). "Three novel functional genetic polymorphisms of ARL6IP5, namely -76GC, 454CA, and 723TG, have been identified to contribute to the development of bladder cancer." (PMID 40253526, 2025). "However, in other cancer tissues including those from bladder cancer, squamous carcinoma of the cervix, squamous cell lung carcinoma, endometrial cancer, and sarcoma of the uterus, a down-regulation of ARL6IP5 was observed." (PMID 40253526, 2025).
cervical (1 paper, 2021). "The reduced expression of miR-142-3p and ARL6IP5 in plasma exosomes from the cancer group may indicate their role as tumor suppressors during cervical tumorigenesis." (PMID 34827689, 2021).
hyperuricemia (1 paper, 2024). An abnormally high level of uric acid. "ARL6IP5 has been reported to be expressed in the kidney and is a potential causal candidate contributing to pleiotropic pathways between CKD and hyperuricemia." (PMID 38879526, 2024).
ischemic stroke (1 paper, 2024). A stroke disorder caused by obstruction of blood flow to the brain, due to thrombotic (local blood clot formation) or embolic (due to a blood clot or other material traveling from another site) event. "DEPs, including GNAQ (G protein subunit α Q), CA3 (carbonic anhydrase 3), ARL6IP5 (ADP ribosylation factor like GTPase 6 interacting protein 5), and SPTB (spectrin β) were identified in total participants between recurrence and nonrecurrence patients with ischemic stroke." (PMID 38420847, 2024).
liver cancer (1 paper, 2025). An epithelial or non-epithelial malignant neoplasm that arises from the liver. "We previously showed that ARL6IP5 is involved in the pathogenesis of HCV-related liver cancer, and this was supported by other studies." (PMID 40253526, 2025). "For example, in liver cancer, ARL6IP5 is more involved in the pathogenesis of hepatitis c virus (HCV)-related cancers." (PMID 40253526, 2025). "The tumor suppressive role of ARL6IP5 in liver cancer has also been reported, where ARL6IP5 was shown to inhibit HCC growth by inhibiting MAPK signaling pathway." (PMID 40253526, 2025).
morphine dependence (1 paper, 2020). Strong dependence, both physiological and emotional, upon morphine. "ARL6IP5/JWA has been associated with increased expression in the amygdala after chronic morphine treatment, and with morphine dependence via the delta opioid receptor." (PMID 33115496, 2020).
schizophrenia (1 paper, 2024). A major psychotic disorder characterized by abnormalities in the perception or expression of reality. "Within the CGE, genes with high expression specificity for two calretinin (CALB2)-positive sub-populations of developing GABAergic neurons were also enriched for schizophrenia genetic liability (CGE-N-1, marker: NRIP3, and CGE-N-2, markers: BEX2, ARL6IP5, VSTM2A)." (PMID 38869145, 2024).
tumor (21 papers, 2012 to 2026). "Other genes, such as ARPC3, POLR2H, WSB2, and ARL6IP5, show opposite association with response in tumor and stroma compartments, respectively." (PMID 41550766, 2026). "Further research is essential to unravel the precise mechanisms by which ARL6IP5 interacts with other molecules, signaling pathways, and tumor microenvironment." (PMID 40253526, 2025). "The role of ARL6IP5 in human cancers is mixed and contradictory: it functions as a tumor suppressor in most cancers, but in some cancers, it acts as an oncogene." (PMID 40253526, 2025). "Vitro experiment showed that ARL6IP5 was downregulated in OC tissues and inhibited tumor cell proliferation." (PMID 38461331, 2024). "Functional studies revealed that ARL6IP5 had tumor-suppressive effects; ARL6IP5-OE consistently decreased cellular proliferation, invasion, migration, adhesion, and wound healing." (PMID 35293383, 2022). "ARL6IP5 functioned as a tumor-suppressor, whose effects were confirmed in both OC and their CisR counterparts." (PMID 35293383, 2022). "In this work we demonstrated that ARL6IP5 is an important prognosticator and tumor-suppressor in OC, with potential to be a novel therapeutic." (PMID 35293383, 2022). "The JWA gene, also called ADP ribosylation-like factor 6 interacting protein 5 (ARL6ip5), serves as a tumor suppressor gene in GC." (PMID 27708243, 2016). "It is also noteworthy that ARL6IP5 also acts as a tumor suppressor in HCC." (PMID 40253526, 2025). "ARL6IP5 can also make tumor cells resistant to drugs via promoting SSBR." (PMID 40253526, 2025). "This suggests that the biological function of ARL6IP5 in a given cancer type may be highly dependent on the tumor microenvironment, emphasizing its complex, context-dependent roles in cancer progression." (PMID 40253526, 2025). "The complex nature of ARL6IP5 is also reflected in the fact that it may exert both tumor-suppressing and oncogenic roles in the same cancer type." (PMID 40253526, 2025). "The biological functions of ARL6IP5 may depend on many factors such as tumor microenvironment and etiological factors." (PMID 40253526, 2025). "ARL6IP5 has tumor-suppressing effects, such as promoting apoptosis." (PMID 40253526, 2025). "Our data suggest that ARL6IP5 is a tumor-suppressor that may be involved in the development, progression, and cisplatin-resistance of OC, in support of its clinical significance; therefore, ARL6IP5 expression may be used as a prognostic biomarker for OC." (PMID 35293383, 2022). "In conclusion, we demonstrated that ARL6IP5 is an independent prognosticator of OC patients with cellular functions of a tumor-suppressor, possibly influencing the development of cisplatin-resistance and progression of OC cells through regulation of DNA repair and apoptosis." (PMID 35293383, 2022). "In addition, ARL6IP5 also acts as a significant prognostic factor and tumor suppressor in OC." (PMID 36561981, 2022). "Despite this down-regulation, conditional ARL6IP5-knockout mice do not show spontaneous tumor formation." (PMID 40253526, 2025).
cancer (19 papers, 2012 to 2025). A tumor composed of atypical neoplastic, often pleomorphic cells that invade other tissues. "Effects of ARL6IP5 expression on cancer hallmark functions of OC cells and their CisR counterparts were examined using proliferation, invasion, migration, adhesion, wound healing, and apoptosis assays." (PMID 35293383, 2022). "At present, researchers have taken the first step toward specifying the cancer therapeutic strategies surrounding ARL6IP5." (PMID 40253526, 2025). "In this article, we aim to provide an overview of the consensus and controversies of the roles of ARL6IP5 in human cancers." (PMID 40253526, 2025). "In this mini-review, we summarized the current understanding on the role of ARL6IP5 in cancers, particularly in the progression of chronic hepatitis virus-related hepatocellular carcinoma, as well as the potential values of ARL6IP5 in cancer therapy." (PMID 40253526, 2025). "Considering the controversial expression patterns and biological functions of ARL6IP5 across different cancers, the therapeutic potential of this gene needs more extensive studies." (PMID 40253526, 2025). "This protein has been extensively studied in the field of cancer metastasis, yet the functions of ARL6IP5 are less well characterized." (PMID 37445677, 2023). "In some cancers, ARL6IP5 exerts its roles through regulating the activity of MAPKs." (PMID 40253526, 2025). "Publicly available Gene Expression Profiling Interactive Analysis (GEPIA) dataset (gepia.cancer-pku.cn) reveals an overexpression of ARL6IP5 in the cancer tissues originating from lymph, brain, kidney, blood, pancreas, skin, and thymus, relative to their respective normal tissues." (PMID 40253526, 2025). "From these findings, we speculate that ARL6IP5 may regulate cancers via PI3K-Akt-mTOR signaling pathway." (PMID 40253526, 2025). "Other studies have shown that targeting the upstream molecules of ARL6IP5 maybe an effective cancer therapeutic strategy." (PMID 40253526, 2025). "Extensive research is needed to clarify the context-dependent role of ARL6IP5 in different cancers." (PMID 40253526, 2025). "ARL6IP5 is abnormally expressed at different levels across different human cancers, hence, its biological role in different cancers may vary." (PMID 40253526, 2025). "The potential application of ARL6IP5 as a therapeutic target in cancer therapy has been reported." (PMID 40253526, 2025). "The differential biological functions of ARL6IP5 across different cancers may be attributed to multifactorial mechanisms." (PMID 40253526, 2025). "ARL6IP5 is a membrane resident protein of ER, mainly studied in the field of cancer." (PMID 37445677, 2023). "In a small study, siRNA ARL6IP5 expression reduced autophagy in cancer cells." (PMID 37445677, 2023). "In contrast, ARL6IP5 downregulation (ARL6IP5-KD) resulted in significantly increased cancer hallmark functions than the scrambled negative control siRNA (si-NC) group at 24, 48, and 72 h in both OC cells and their CisR counterparts (p < 0.05)." (PMID 35293383, 2022). "ADP-ribosylation-like factor 6 interacting protein 5 (Arl6ip5), which belongs to the prenylated rab-acceptor-family, has an important role in exocytic protein trafficking, glutathione metabolism and involves in cancer progression." (PMID 25321471, 2014). "However, ARL6IP5 also functions as an oncogene in some cancers." (PMID 40253526, 2025). "However, the biological roles of ARL6IP5 in cancers are controversial." (PMID 40253526, 2025). "Therefore, both up-regulation and down-regulation of ARL6IP5 may be utilized as strategies in cancer therapy." (PMID 40253526, 2025).
cancer (continued). "ARL6IP5 (ADP-ribosylation-like factor 6 interacting protein 5) plays an important role in a variety of physiological or pathological processes, including in cancers." (PMID 40253526, 2025). "Expression profiling shows that most of cancers, including HCC, express high level of ARL6IP5." (PMID 40253526, 2025).
neurodegenerative disease (3 papers, 2018 to 2024). A disorder of the central nervous system characterized by gradual and progressive loss of neural tissue and neurologic function. "To study the role of ARL6IP5 in aging and neurodegenerative diseases, we checked the age-dependent (4, 8, and 12 months) change in the level of ARL6IP5 in the wild-type C57BL6 mouse brain (WT) and PD transgenic mouse model (A53T mutant) (Tg)." (PMID 37445677, 2023). "This indicates a direct role of ARL6IP5 in aging and PD-like neurodegenerative diseases." (PMID 37445677, 2023).
kidney disease (1 paper, 2024). "Furthermore, the study of ARL6IP5 and kidney disease is limited, so the impact of ARL6IP5 on leukocytes and kidney disease warrants further investigation." (PMID 38879526, 2024).
ARL6IP5 also shares sentences with these, for which no sentence is quoted: melanoma (9 papers); lung carcinoma (4); esophageal squamous cell carcinoma (3); infection (3); cardiovascular disease (2); Hyperglycemia (2); malaria (2); non-small cell lung carcinoma (2); Obesity (2); osteosarcoma (2); pancreatic cancer (2); skin cancer (2); atherosclerosis (1); Bardet-Biedl syndrome (1); benign tumors (1); coeliac disease (1); Cognitive impairment (1); endothelial dysfunction (1); enteritis (1); glioblastoma (1); hemochromatosis (1); heroin addiction (1); invasive carcinoma (1); iron overload (1); lung squamous-cell-carcinoma (1); lymph node metastasis (1); papilloma (1); retinitis pigmentosa (1); sickle cell anemia (1); skin papilloma (1).
A further 4 diseases each share a sentence with ARL6IP5 in 1 paper.